DNTTIP1 (deoxynucleotidyltransferase terminal interacting protein 1)
Description:
Increases DNTT terminal deoxynucleotidyltransferase activity (in vitro). Also acts as a transcriptional regulator, binding to the consensus sequence 5'-GNTGCATG-3' following an AT-tract. Associates with RAB20 promoter and positively regulates its transcription. Binds DNA and nucleosomes; may recruit HDAC1 complexes to nucleosomes or naked DNA.
Synonyms: TdIF1; C20orf167; dJ447F3.4
Tractability: PROTAC: ubiquitination databases record sites on it; its protein half-life has been measured.
Gene: Protein-coding gene on chromosome 20 (45,791,946 to 45,811,427, forward strand). Ensembl gene ENSG00000101457.
Subcellular location: Nucleus
Subcellular location (Human Protein Atlas): Mitotic chromosome; Nucleoli; Nucleoli rim; Nucleoplasm
Pathways (Reactome):
Cell-Cell communication: Negative Regulation of CDH1 Gene Transcription
Gene Ontology:
Molecular function: DNA binding; nucleosome binding; protein binding; protein homodimerization activity
Biological process: chromatin organization; regulation of embryonic development
Cellular component: chromosome; histone deacetylase complex; nucleolus; nucleoplasm; nucleus
Genetic constraint (gnomAD): Loss-of-function variants: 21 observed, 44.95 expected, observed/expected ratio (o/e) 0.47, 90% interval 0.33 to 0.67. The upper end of that interval is the gene's LOEUF score, 0.67, which puts it in group 2 of 6, group 1 being the genes least tolerant of losing a copy. Missense variants: 257 observed, 393.12 expected, observed/expected ratio (o/e) 0.65, 90% interval 0.59 to 0.73. Synonymous variants: 125 observed, 140.68 expected, observed/expected ratio (o/e) 0.89, 90% interval 0.77 to 1.03.
Homologues: Orthologues: chimpanzee DNTTIP1 (100% identical), dog DNTTIP1 (98% identical), pig DNTTIP1 (98% identical), rabbit DNTTIP1 (97% identical), mouse Dnttip1 (96% identical), rat Dnttip1 (96% identical), guinea pig DNTTIP1 (95% identical), macaque DNTTIP1 (77% identical), tropical clawed frog dnttip1 (67% identical), zebrafish ube2c (34% identical), Caenorhabditis elegans saeg-2 (23% identical).
Diseases named in the same sentence as DNTTIP1 in open-access papers:
DNTTIP1 is named in the same sentence as 24 diseases in open-access papers, as found by Europe PMC text mining. Sharing a sentence is not in itself a finding about the gene and the disease. The quoted sentences say what the papers report.
non-small cell lung carcinoma (4 papers, 2018 to 2025). A group of at least three distinct histological types of lung cancer, including non-small cell squamous cell carcinoma, adenocarcinoma, and large cell carcinoma. "Furthermore, DNTTIP1 or ELMSAN1 loss in mESCs did not alter the proliferation rate or cell cycle profile, in contrast to the reported growth-promoting function of DNTTIP1 in oral and non-small cell lung cancer." (PMID 32297854, 2020).
oral squamous cell carcinomas (2 papers, 2021).
acute myelocytic leukemia (1 paper, 2021). "For example, a recent study reported that DNTTIP1 expression could be a specific biomarker present in acute myelocytic leukemia (AML)." (PMID 35265097, 2021). "Former bioinformatics analysis indicated that DNTTIP1 could predict the survival of patients with acute myelocytic leukemia." (PMID 35265097, 2021).
cervical squamous cell carcinoma (1 paper, 2021). A squamous cell carcinoma arising from the cervical epithelium. "In many other cancer types such as adrenocortical carcinoma (ACC), breast invasive carcinoma (BRCA), cervical squamous cell carcinoma, and endocervical adenocarcinoma (CESC), DNTTIP1 was also significantly overexpressed when compared with normal tissues." (PMID 35265097, 2021).
fibrosis (1 paper, 2021). the formation of excess fibrous connective tissue in an organ or tissue in a reparative or reactive process. "A high level of DNTTIP1 expression was associated with poor prognosis of HCC patients with a fibrosis Ishak score of 5/6, thus indicating that the high association between DNTTIP1 expression level and survival may be influenced by the degree of hepatic fibrosis." (PMID 35265097, 2021).
myeloid leukemia (1 paper, 2024). A clonal proliferation of myeloid cells and their precursors in the bone marrow, peripheral blood, and spleen. "MiDAC has been shown to contain protein subunits MIDEAS, HDAC1, HDAC2 and DNTTIP1 in myeloid leukemia K562 cells and human T lymphocyte CEM cells." (PMID 38781120, 2024).
cancer (5 papers, 2018 to 2022). A tumor composed of atypical neoplastic, often pleomorphic cells that invade other tissues. "DNTTIP1 can enhance DNA polymerase activity and form a complex with histone deacetylase (HDAC); hence, it has a close relationship with cancer progression." (PMID 35265097, 2021).
tumor (3 papers, 2018 to 2021). "As many pathways contribute to tumor formation, high DNTTIP1 expression associated with poor survival may be related to active signaling pathways in HCC." (PMID 35265097, 2021). "We employed Spearman’s correlation to show the association between the expression level (TPM) of DNTTIP1 and immune cell infiltration level quantified by ssGSEA in the HCC tumor microenvironment." (PMID 35265097, 2021). "This indicates that overexpression of DNTTIP1 promotes Th2 cell immune response and infiltration in tumor progression." (PMID 35265097, 2021). "DNTTIP1 was found to be upregulated with amplification in tumor tissues in multiple HCC cohorts." (PMID 35265097, 2021).
DNTTIP1 also shares sentences with these, for which no sentence is quoted: lung carcinoma (3 papers); adenocarcinoma (2); lung adenocarcinoma (2); lymph node metastasis (2); breast carcinoma (1); colorectal cancer (1); connective tissue disorder (1); endocervical adenocarcinoma (1); endometrial cancer (1); Hepatic fibrosis (1); hepatocellular carcinoma (1); leukaemia (1); nasopharyngeal carcinoma (1); oral cancer (1); ovarian carcinoma (1); squamous cell carcinoma (1).